INS (insulin)
Diseases named in the same sentence as INS in open-access papers (continued):
Sharing a sentence is not in itself a finding about the gene and the disease.
Insulin resistance (continued). "Regarding T2DM, it has been described how ADMSCs may improve insulin resistance, as they may activate different signaling pathways, including GLUT-4 signaling and PPAR-γ activation, as they may decrease pro-inflammatory cytokines and insulin desensitizing adipokines secretion." (PMID 37445852, 2023). "Improved insulin sensitivity was the expected secondary outcome of antidiabetic treatment; hence, the insulin tolerance test (ITT) was performed, and mathematically modeled ITT function was calculated in the experimental week 18 when we assumed insulin resistance could be developed." (PMID 37929025, 2023). "Exercise intervention may inhibit the overactivation of NLRP3 inflammasome, leads to a decreased level of inflammatory cytokine IL-1β, which further fails to induce hepatic insulin resistance, thus enhancing insulin sensitivity and improving insulin resistance." (PMID 36817440, 2023). "However, in the context of insulin resistance, there is an impaired activation of the PI3K-Akt pathway, whereas the activation of the MAPK pathway remains unaffected, thus producing a decrease in insulin-induced vasodilation and contributing to the development of hypertension in the long term." (PMID 37833890, 2023). "In the future, we will examine in all women recruited in the Diana-5 study how IGF-1 levels, insulin resistance, and fasting insulin levels in women without MetS may influence the incidence of relapses, secondary BC, and metastases compared to women diagnosed with MetS." (PMID 37106164, 2023). "An easier, albeit less accurate method of measurement, is the Homeostasis Model Assessment of Insulin Resistance (HOMA-IR) which requires the measurement of fasting plasma Insulin levels, which may not be widely available and inaccurate due to improper standardization." (PMID 36788883, 2023). "Additionally, using non‐diabetic participants at baseline could be another potential reason for the absence of significant changes in insulin resistance and plasma levels of insulin and glucose." (PMID 35451536, 2023). "Therefore, we can surmise that AKG could potentially have therapeutic effects in humans with obesity and insulin resistance; however, the role of AKG in cellular metabolism in regulation of insulin-dependent metabolic responses needs to be studied in more detail." (PMID 38234967, 2023). "Glucose metabolism is impaired in girls with CPP, as they have elevated levels of basal insulin, indicating a possible early onset of insulin resistance; this parameter may change or not following GnRH therapy, remaining high and even increasing in girls with a higher BMI." (PMID 37371772, 2023). "Consequently, mice lacking liver IPMK showed symptoms of hepatic insulin resistance, including reduced glycogen storage and increased gluconeogenesis in the presence of insulin, and the tendency to gain more weight than their wildtype litter mates on a high fat diet." (PMID 35743190, 2022). "In the MCD-fed animals, the absence of systemic insulin resistance and the presence of hepatic insulin resistance were found; thus, this model may help to delineate NASH pathogenesis in the absence of confounding parameters and to identify the involvement of non-insulin resistant mechanisms." (PMID 35743260, 2022). "Interestingly, however, a supraphysiological dose of insulin could not rescue the skeletal muscle insulin resistance in PCKO mice or C646 treatment." (PMID 34813504, 2022). "However, insulin exposure did not affect the number of cells that responded to shear stress for the native diabetic OA phenotype, indicative of lower insulin responsiveness and potentially diabetic insulin resistance." (PMID 35265601, 2022). "As brain insulin resistance can be observed many years before the onset of cognitive symptoms in AD, we investigated whether the brains of the mice with humanized APOE ε4/ε4 livers exhibited changes in key markers of the insulin signaling pathway in the cortex and hippocampus." (PMID 35418601, 2022).
Insulin resistance (continued). "In this way, (C16:0) ceramides may contribute to the selective insulin resistance paradox, wherein the insulin-resistant liver fails to suppress glucose production but continues to stimulate lipogenesis, which is a central mechanism in the pathophysiology of hepatic steatosis and type 2 diabetes." (PMID 35789435, 2022). "In addition, the finding that unsaturated FA can induce insulin resistance without elevating ceramide content suggests that the ceramide-mediated impairment of distal insulin signalling may not be mandatory for lipid-induced insulin resistance." (PMID 34704121, 2022). "The variation might be attributed to the majority of participants in this were diabetics without inherent complications in which, patients who have insulin resistance with a decrease in excretion of substances due to the reduced effects of insulin action, in turn, a mild effect on erythropoietin." (PMID 35377899, 2022). "In addition, pancreatic fat accumulation may play a pivotal role during the intermediary step of the disease and negatively affect insulin secretion only via persistent insulin resistance, when β-cells can no longer compensate for the increased insulin demand." (PMID 35327494, 2022). "Hence, the beneficial effect of αCD does not require an increase in insulin production, suggesting that even people with insulin resistance might benefit from αCD." (PMID 36349072, 2022). "Moreover, PC-1 expression is higher in the fibroblasts isolated from nonobese nondiabetic insulin-resistant subjects, suggesting that PC-1 may play a role in the development of insulin resistance." (PMID 36589630, 2022). "Therefore, we hypothesize that despite insulin resistance, perhapsat this age, insulin secretion by beta cells is not impaired enough to changeglucose and TAG concentrations." (PMID 35857997, 2022). "In case the insulin values are elevated, depending on how high and whether the initial and final findings are higher, as well as whether the glucose values are normal or not, the diagnosis of insulin resistance is made, prediabetic conditions, or diabetes." (PMID 35628058, 2022). "In addition, proband A did not respond to 50 units of insulin/day, and her triglyceride levels were 50.21 mmol/L, so she might be in a state of insulin resistance." (PMID 35992135, 2022). "We observed significantly higher fasting insulin levels, serum triglyceride levels, and HOMA-IR reflecting hyperinsulinemia and possibly an insulin-resistant state among primary hypertension patients with no other causally linked factors for insulin resistance." (PMID 35482462, 2022). "The AAP group did have qualitatively higher values of glucose AUC, insulin AUC, and HOMA-IR compared to the mood stabilizer group, however, these differences were not statistically significant which would have been hypothesized based on the known effects of AAPs on insulin resistance." (PMID 35204022, 2022). "In subsequent sections, we focus primarily on non-pancreas colocalizations for their relevance in insulin resistance and insulin action; however, other investigators interested in the β-cell-mediated pathways of T2D may find these pancreas-specific colocalizations especially relevant." (PMID 35292083, 2022). "Namely, in the elderly, T2D may be driven by slower insulin secretion in response to intestinal incretins, and insulin resistance may not be as prevalent, and if present it is mostly related to body composition (e.g., lower muscle mass for glucose uptake) and to physical inactivity." (PMID 36558885, 2022). "In addition, roflumilast has been shown to improve peripheral insulin sensitivity in adults with prediabetes and overweight/obesity, suggesting that PDE4 may participate in the pathophysiology of peripheral insulin resistance through direct and/or indirect effects." (PMID 35629988, 2022).
Insulin resistance (continued). "While no group differences for insulin resistance were found in the present study, African American women did have elevated insulin at 2 h postprandial, indicating that even in healthy females, insulin sensitivity may play a predominant role in metabolic flexibility." (PMID 36232212, 2022). "Interestingly, TNF-α can induce insulin resistance in mice, and a recent study in flies observed that fat body-secreted Egr targets insulin-producing cells to inhibit the expression of dILPs, indicating a conserved role for TNF-α/Egr signaling in antagonizing insulin/IGF signaling." (PMID 35319749, 2022). "However, mismatch between peripheral and hepatic insulin sensitivity may better describe subgroups of adolescents with IGM compared to peripheral insulin resistance alone, particularly in the setting of physiologic pubertal insulin resistance." (PMID 36518108, 2022). "Moreover, the noticeable reductions in blood glucose, insulin, and HOMA-IR, basic indicators of insulin resistance, that we observed following the program, suggest that exercise may increase anti-inflammatory cytokine levels and improve insulin resistance." (PMID 36292427, 2022). "In prediabetic conditions, moderate hyperglycemia and peripheral insulin resistance do not immediately result in the progression of T2D due to the β-cell compensatory response, where increases in β-cell mass and insulin secretion are competent in meeting the elevated demand for insulin." (PMID 35929791, 2022). "Considering that OC can stimulate insulin secretion and has been shown to have a beneficial effect on glucose metabolism in animal and human studies, we speculated that the consistently lower levels in OC in the postpartum AGM group was an insufficient compensation for insulin resistance." (PMID 35321337, 2022). "However, intravenous insulin infusion in patients with type 2 diabetes does not change NT-proBNP concentrations, which may be due to insulin resistance." (PMID 35215487, 2022). "This advantage of the application in subjects with insulin-resistance reflects the nonlinear nature of the equations used in the new model, which as a result accounts more appropriately for the saturation effects in the context of higher glucose and/or insulin concentrations." (PMID 36271244, 2022). "Altogether, the evidence shows that the interaction between arsenic exposure and insulin signaling is not necessarily linear, and factors such as sex, development window, nutrient intake and genetic background will influence the development of insulin resistance." (PMID 35651975, 2022). "Similarly, fasting insulin might not have been the ideal measure of insulin resistance, although it is a good measure for hyperinsulinemia, which is likely the major cancer link." (PMID 35048536, 2022). "Moreover, since oxidative stress also plays a pivotal role in the development of insulin resistance, the presence of antioxidant compounds in CSAT+®, such as gallotannins and flavonols, may also be involved in its insulin sensitizing effects in peripheral tissues." (PMID 36139877, 2022). "Therefore, especially in the presence of insulin resistance, in which the flux of free fatty acids (FFAs) from adipose is not suppressed by insulin, the elevated rate of lipogenesis may be a significant source of stored triacylglycerol in the liver." (PMID 36558510, 2022). "While the verification of the body weight gain has performed almost consistently, few studies have investigated whether HFD treatment produced insulin resistance, as measured by elevated fasting plasma glucose and insulin, and the measure of leptin levels has also not been routinely done." (PMID 35887310, 2022). "Consequently, insulin-resistant and dysfunctional WAT is no longer capable of expanding appropriately to store excess energy in a safe manner, causing ectopic lipid accumulation and progressive systemic insulin resistance." (PMID 33206203, 2021).
Insulin resistance (continued). "The effects of androgens on insulin signaling are not clear, since some studies reported that testosterone supplementation can improve insulin sensitivity, while others have demonstrated that testosterone supplementation worsens hepatic insulin resistance in a male mouse model of T2D." (PMID 34572151, 2021). "An increase in insulin levels not connected to insulin resistance could result counterintuitive since the hyperinsulinemic state is traditionally viewed as a compensatory response to insulin resistance." (PMID 33909378, 2021). "However, insulin-induced activation of the mitogen activated kinases (MAPK) pathway is not affected by insulin resistance, which results in the thickening of vascular wall and increased production of the vasoconstrictor endothelin-1 by the endothelium contributing to the development of hypertension." (PMID 34356299, 2021). "Constitutive activation of insulin signaling pathway at target tissues due to increased and sustained insulin levels, initiates several negative feedback loops, putting brakes on the initial steps of insulin signaling, contributing to pathological condition known as insulin resistance." (PMID 34319011, 2021). "Moreover, ginsenoside Re could promote insulin secretion, stimulate cannabinoid type 1 receptor (CB1) and CaMKK β to activate the AMPK signaling pathway, inhibit insulin resistance induced by TNF-α, and improve blood glucose uptake and diabetic nephropathy, so as to exert the goal of anti-diabetic." (PMID 34771066, 2021). "However, normal-weight individuals may also be insulin resistant, suggesting that overall adiposity is not the sole determinant of insulin resistance." (PMID 34869524, 2021). "Additionally, the development of insulin resistance is contributed to by pro-inflammatory cytokines such as tumor necrosis factor α (TNF-α), interleukin 1 (IL-1), and interleukin 6 (IL-6), which affect insulin signaling by inhibition of IRS-1 through serine phosphorylation." (PMID 34299269, 2021). "Altogether, these findings suggest that different forms of HIIT and SIT are impactful at altering insulin sensitivity in populations with increased insulin resistance; however, they may not be as beneficial for individuals without pre‐existing insulin resistance." (PMID 34110721, 2021). "To determine whether metformin protects against insulin resistance induced by HUA in cardiomyocytes, we exposed primary cardiomyocytes to HUA, pre‐treated them with metformin and then quantified the uptake of glucose with 2‐NBDG, a fluorescent glucose analog, after insulin stimulation." (PMID 34053175, 2021). "Moreover, evidence is lacking whether placental iodine could play a role in the insulin homeostasis, insulin resistance, and β-cell activity." (PMID 33602219, 2021). "However, an increasing amount of evidence has demonstrated that in the crosstalk between the gut microbiota and insulin resistance, the former may exert dual effects, beneficial or non-beneficial, on insulin regulation." (PMID 35111696, 2021). "Additionally, the continuation of insulin resistance can lead the beta cells of the pancreas to get to a point where they can no longer provide the high amounts of insulin secreted before, leading to a drop in insulin secretion and further failure of glucose homeostasis." (PMID 34754676, 2021). "In non-diabetic obese individuals, insulin resistance is increased but β-cell mass and insulin secretion are also increased to maintain glucose control, suggesting that healthy β-cells may proliferate to adapt to increased insulin demand." (PMID 34531828, 2021). "Our results of a negative association between insulin sensitivity and the FTO risk allele in males only, are not in accordance with studies in children and adolescents that find a positive association between insulin resistance and the FTO risk allele mainly in females." (PMID 33684170, 2021).
Insulin resistance (continued). "Since the effect of insulin on PG and plasma potassium is independent, insulin-induced cellular potassium uptake is not affected by insulin resistance in type 2 diabetes, which could explain the difference in plasma potassium in spite of almost similar changes in PG." (PMID 34085953, 2021). "Thus, we could conclude that the PaC homograft mice demonstrated the reduction of insulin secretion after high glucose stimulation, but no dramatic sign of peripheral insulin resistance, while the pancreatic derived miR-19a plays an important role." (PMID 34512170, 2021). "Also, regular estradiol administration (in combination with antiandrogenic compounds) in transwomen may affect energy metabolism by increasing total body fat, fasting insulin, and HOMA of insulin resistance (HOMA-IR), thereby reducing peripheral insulin sensitivity." (PMID 34342596, 2021). "The intraperitoneal insulin tolerance test showed a similar impaired glucose reduction in the early phase (30 and 60 min after insulin loading) between the 2 treatment groups, indicating that the insulin resistance did not deteriorate further with the Pg treatment." (PMID 34526589, 2021). "Similarly, the fasting insulin level of H group was also significantly divergent from that of COS-treated HC group and low-fat fed L group; the HOMA-IR results indicated insulin resistance level was also significantly higher in the H group than in the L group and the HC group." (PMID 34660667, 2021). "Indeed, with the exception of insulin-induced insulin resistance, virtually every molecular mechanism proposed to explain insulin resistance in obesity since the Randle glucose-FFA cycle, indicate elevated circulating FFA levels as a major driver of insulin resistance [2,3,]." (PMID 33712379, 2021). "It has been hypothesized that individuals with isolated IFG have hepatic insulin resistance with abnormal hepatic glucose production, whereas those with isolated IGT predominantly have muscle insulin resistance and normal or slightly reduced hepatic insulin sensitivity." (PMID 34831236, 2021). "In addition, QC exhibited antiobesity and anti-insulin resistance effects in the adipocytes of obese rats and resulted in the downregulation of peroxisome proliferator-activated receptor gamma (PPAR-γ) mRNA in liver, muscle, and adipose tissue in high-fat diet-induced insulin-resistant rats." (PMID 33669133, 2021). "However, insulin as a major factor downregulating SHBG production does not come along with the fact that obese subjects are characterized by insulin resistance, and, to the best of our knowledge, the molecular mechanism by which insulin reduces SHBG production has not yet been described." (PMID 33689083, 2021). "While enhanced insulin secretion and reduced insulin clearance could both potentially cause hyperinsulinemia, it has been shown that decreased insulin clearance rather than increased insulin secretion contributes to hyperinsulinemia during weight gain to compensate for insulin resistance." (PMID 34572340, 2021). "Moreover, since AD has no successful treatment and brain insulin resistance may be significantly affected; clinical trials on insulin have been carried out." (PMID 34975451, 2021). "A normal/high T/E2 ratio has proven to be able to reduce insulin resistance by lowering insulin and glucose levels, without body composition changing in nonobese adult men, highlighting a direct and specific role of T in coregulating the insulin secretion and activity." (PMID 32411230, 2020). "However, since insulin resistance status is an individual-level characteristic, we could not adjust for donor without removing the signal of interest (insulin sensitivity status)." (PMID 33362275, 2020).